IL1B (interleukin 1 beta)
Diseases named in the same sentence as IL1B in open-access papers (continued):
Sharing a sentence is not in itself a finding about the gene and the disease.
melanoma (continued). "In this study, LINC01198 is identified highly upregulated and acts as driving factor, which associates with TAOK1/TAOK2 to activate Hippo pathway and transcriptionally induce IL-1B expression for supporting melanoma resistance against vemurafenib." (PMID 41145465, 2025). "Collectively, we have demonstrated both of exogenous recombinant human IL-1β and melanoma cell-secreted IL-1β can promote the viability of vemurafenib-resistant A375R melanoma cells against vemurafenib." (PMID 41145465, 2025). "To verify the role of tumor-derived IL-1β in vemurafenib-resistant melanoma, we knocked down IL1B in A375R cells which were verified by Western blot." (PMID 41145465, 2025). "To validate the role of IL-1β induced by vemurafenib treatment in melanoma, we evaluated the cell viability in response to various levels of IL-1β." (PMID 41145465, 2025). "Ubiquitin-conjugating enzyme E2 (UBE2), participating in various skin pathologies including melanoma, plays a pivotal role in inflammation by promoting nuclear factor kappa B (NF-κB) activation, pro-IL-1β ubiquitination and its proteasomal degradation." (PMID 40427427, 2025). "Activation of the pyroptotic pathway increases the secretion of IL‐1β, which can effectively inhibit the growth of melanoma." (PMID 41025546, 2025). "The expression of the two zebrafish pro-inflammatory cytokines il1b and il8 was tested in the larval melanoma transplants (MT), and in control larvae (CTL) injected with PBS in the SB." (PMID 40449994, 2025). "Increased IL-1β expression was seen in several human malignancies, including melanoma, colon, breast, and lung tumors." (PMID 39999222, 2025). "Melanoma cells exhibit IL-1β-driven autoinflammatory properties, partially regulated by the MAPK/ERK pathway and transcription factor ATF4." (PMID 40558540, 2025). "In melanoma, this activity in CAFs is promoted by increased expression of IL-1β, IL-6, IL-8, C-X-C motif chemokine ligand 8 (CXCL8), and various types of metalloproteinases." (PMID 40725022, 2025). "Pro-inflammatory cytokines like IL-1β and IL-8 are critical in promoting melanoma cell growth and invasiveness." (PMID 40636453, 2025). "In agreement, late stage melanoma patients exhibited high levels of IL-1β in their serum and presented with increased MDSCs and Tregs." (PMID 38391959, 2024). "To further validate the functional relevance of tumor-enriched populations, we performed IL-1β-enriched NT GSDMD treatment of B16F10 melanoma in immunocompetent C57BL/6 mice with depleted NK1.1 and CD8β-expressing cells." (PMID 39737979, 2024). "IL‐1β in melanoma elicits inflammation and the expansion of highly immunosuppressive myeloid‐derived suppressor cells." (PMID 38327091, 2024). "It has been shown that IL-1β expression is upregulated in many solid tumors, including melanoma, colon cancer, and lung cancer." (PMID 39795180, 2024). "In a study of melanoma cell lines, the investigators found that inhibiting NLRP3 using OLT1177, caused suppression of IL-1β mediated inflammation by disrupting the IL-1β/IL-6/STAT3 axis." (PMID 39516433, 2024). "On the other hand, different authors have consistently maintained that EDPs induce the production and/or secretion of IL-1α, IL-1β, and IL-6 in ligamentum flavum cells, synovial cells, and melanoma cell lines." (PMID 38967692, 2024). "PANX1 has been proposed as a potential target to regulate anti‐tumor immunity in melanoma due to the PANX1‐mediated release of proinflammatory cytokine IL‐1β (reviewed in Ref." (PMID 38327091, 2024). "It is interesting to note that B16-F10 tumors (Mock treated) grow less in Caspase-1/11-/-, Caspase-11-/- and IL-1R-/-, which confirms another study that showed the importance of IL-1β signaling in B16 melanoma tumor progression." (PMID 38835781, 2024). "Therapies that inhibit the NLRP3 inflammasome can block melanoma migration by suppressing the secretion of IL-1β and IL-18 cytokines and/or activating natural killer cells." (PMID 39275245, 2024).
melanoma (continued). "In the context of melanoma, IL-1B has been demonstrated to enhance the antitumor capabilities of T helper 1 (Th1) cells." (PMID 37895833, 2023). "EGCG demonstrated a major role in suppressing melanoma cell survival and prevented NF-κB activity, which consequently led to a decrease in IL-1β production in melanoma cells." (PMID 37838685, 2023). "Their data emphasize the protein’s role as an upstream regulator in melanoma and stromal cells, as cancer IL-1β promotes gene expression in CAFs through the secretion of growth factors and chemokines." (PMID 37627054, 2023). "In conclusion, our work shows evidence of extremely low NLRP3 expression and IL‐1β secretion by melanoma cells and highlight differences between CM and UM." (PMID 36707938, 2023). "Constitutively activated NLRP3 in melanoma secretes IL-1β that initiates IL-6 secretion through stimulating IL-1R." (PMID 36932407, 2023). "It has also been reported that low doses of EGCG suppressed melanoma cell growth through inhibition of NF-kB with parallel reduction of IL-1β secretion from melanoma cells." (PMID 36768978, 2023). "The invasive potential of human melanoma cell lines correlates with the ability to stimulate host stromal fibroblasts, a function that is orchestrated by IL1β expression confirming a key role of this factor in melanoma invasion and metastasis." (PMID 37762344, 2023). "We profiled the IL-12 virotherapy-induced immune equilibrium in murine melanoma, identifying blockade of innate inflammatory cytokines, tumor necrosis factor alpha (TNFα), IL-1β, or IL-6 as possible synergistic interventions." (PMID 37461742, 2023). "BRAF V600E melanoma cells have been found to produce key cytokines involved in inflammation such as IL-1β, IL-6, IL-8, and TGF-β as signals, for instance, for neutrophil recruitment." (PMID 37627054, 2023). "M1-type macrophages are involved in the tumor immune process of melanoma by secreting cytokines, such as IL-1β, TNF-α, IL-12 and IL-18." (PMID 37762054, 2023). "In melanoma, JNK has been found to be implicated in melanoma growth and progression, initiated through activation by IL-1β, whose receptors are highly expressed on Th2 cells." (PMID 36612301, 2023). "The shear-resistant arrest of B78chOVA melanoma cells to IL-1β-stimulated pMBMECs was significantly enhanced compared to TNF-α-stimulated pMBMECs." (PMID 37894438, 2023). "In melanoma, macrophage-derived NLRP3/IL-1β pathway promotes migration and invasion of melanoma cells, which can be blocked through NLRP3 knockout, caspase-1 knockout, or NLRP3 inhibitor, celastrol." (PMID 36932407, 2023). "An elevated frequency of IL-1β was positively correlated with the level of M-MDSCs in the peripheral blood of advanced melanoma patients." (PMID 38304256, 2023). "We determined that the percentage of melanoma cell intercalation into IL-1β-stimulated pMBMECs was still significantly increased compared to TNF-α-stimulated pMBMECs." (PMID 37894438, 2023). "Subsequently, we challenged the IL‐1β−/− mice with different solid tumor cells (melanoma B16‐F10 cells and Lewis lung carcinoma cells) via tail vein after surgeries." (PMID 37585564, 2023). "Taken together, we here demonstrate increased shear-resistant arrest of melanoma cells IL-1β-stimulated pMBMECs compared to the TNF-α stimulated pMBMECs." (PMID 37894438, 2023). "From 60 min after the start of the experiment, significantly more melanoma cells intercalated into IL-1β-stimulated pMBMECs than into TNF-α stimulated pMBMECs." (PMID 37894438, 2023). "An autoinflammatory loop has been reported in melanoma, where tumor cells produce IL-1β and IL-6 through IL-1β/IL-6/STAT3 axis allowing for the activation of MDSCs." (PMID 36932407, 2023). "Ablation of the NLRP3/pro-IL-1β inflammasome rewires MDSC function, promotes melanoma and breast cancer regression, and causes cisplatin resistance." (PMID 36911674, 2023).
melanoma (continued). "It is considered that IL-1β has various effects on different cells of the tumour microenvironment, maintaining survival and proliferation of melanoma cells, immune suppressor cells, and macrophages while promoting invasion and metastasis." (PMID 35334544, 2022). "In the present study, we provide evidence that the melanoma micromilieu enhances the production of CCL2, IL-8, IL-1β, and C3/C3a by MCs, factors associated with tumor progression." (PMID 35669782, 2022). "Our results demonstrate that the NLRP3/IL-1β pathway is activated in MDSCs in melanoma-bearing animals." (PMID 36032139, 2022). "IL-1β induced the migration of melanoma cells; however, this migration was attenuated by UK356618, an MMP-3 inhibitor." (PMID 36445856, 2022). "This enzyme cleaves and promotes the maturation of pro-inflammatory cytokines such as interleukin-1β (IL-1β) and interleukin-18 (IL-18) by macrophages, dendritic cells, and some tumor cells, such as human melanomas." (PMID 36144933, 2022). "The study based on melanoma cell line and melanocytes proved that BRAF V600E mutation-induced transcription of IL1B." (PMID 35163468, 2022). "We observed that a dose-dependent upregulation of MMP-3 release in culture media of melanoma cells stimulated with IL-1β at the range of 0 to 100 pM for 24 h." (PMID 36445856, 2022). "Taken together, these data suggest that melanoma-secreted cytokines such as TGF-β and IL-1β contribute to the melanoma microenvironment by upregulating C3 expression in MAMCs, thus inducing an MC phenotype switch that negatively impacts melanoma prognosis." (PMID 35669782, 2022). "In the present study, we showed that NF-κB p65/RelA contributes to MMP-3 expression induced by IL-1β in melanoma cells." (PMID 36445856, 2022). "IL-1β is shown to be constitutively expressed to stimulate angiogenesis and to promote tumor growth and metastasis in some mouse melanoma models." (PMID 35743930, 2022). "Then we evaluated the effect of IL-1β on MMP-3 mRNA expression in p65/RelA- or p105-depleted melanoma cells." (PMID 36445856, 2022). "Moreover, the progression of melanoma was found to be associated with elevated concentrations of IL-1β as compared to patients with stable disease, and enrichment of circulating monocytic MDSCs significantly correlated with a decreased progression free survival of melanoma patients." (PMID 36032139, 2022). "Taken together, MMP-3 plays an important role in the cellular migration of IL-1β-treated melanoma cells via protease activity." (PMID 36445856, 2022). "The significant inhibition in IL-1β-mediated-MMP-3 mRNA expression was observed in the cells pretreated with TPCA-1 (10 μM) for 1 h, suggesting that the activation of NF-κB is involved in MMP-3 mRNA expression in IL-1β-stimulated canine melanoma cells." (PMID 36445856, 2022). "PCR analysis showed an increased expression of IL1B in tumor samples from melanoma, colon and lung cancer patients, as did our whole RNA sequencing on tumor samples from both AA and CA patients." (PMID 36531053, 2022). "In this regard, melanoma-derived IL-1β works as a stimulator of angiogenesis, tumour growth, invasion, and metastasis, the influence of the inflammasomes depending on the tumour cell types." (PMID 35334544, 2022). "Such p65/RelA and p105 phosphorylation induced by IL-1β was reduced in melanoma cells pretreated with TPCA-1." (PMID 36445856, 2022). "The data thus confirmed the prominent appearance of IL-1β in the SASP of cytokine-induced senescent melanoma cells, which was already indicated in the qPCR and Proteome Profiler arrays (b and Figure A2a, b)." (PMID 35563820, 2022). "In turn, TAMs secrete the melanoma-stimulating molecules angiotensin, COX-2, IFN-γ, and IL-1β, supporting melanoma growth and metastasis." (PMID 36181568, 2022). "Previously, we observed that p65/RelA and p105 activation are necessary for COX-2 expression mediated by IL-1β in canine melanoma cells." (PMID 36445856, 2022).
melanoma (continued). "Melanoma cells are able to secrete IL-1α and IL-1β, which in turn upregulate IL-6, IL-8, the intracellular adhesion molecule-1 (ICAM-1), and the vascular cell adhesion molecule-1 (VCAM-1) expression in endothelial cells." (PMID 35626056, 2022). "In the present study, we demonstrate that the canonical NF-κB signaling pathway, NF-κB p65/RelA activation, is involved in the IL-1β mediated-MMP-3 expression in canine melanoma cells." (PMID 36445856, 2022). "In a melanoma model, IL-1β expressed by myeloid cells and other pro-inflammatory cytokines induce VEGF expression in endothelial cells, creating a microenvironment favorable for early tumor development." (PMID 36293159, 2022). "The concentrations of IL-1β, TNFα, and IL-10 were assessed in the peripheral blood plasma obtained from the healthy animals (control) and animals bearing S91 melanoma tumors at different stages of growth." (PMID 35053477, 2022). "Treg-specific ablation of GPX4 induces robust generation of mitochondrial superoxide and production of IL-1β to facilitate Th17 responses, both of which potentiate antitumor immunity and repress tumor growth in melanoma." (PMID 36003368, 2022). "IL-17A induces the expression of inflammatory cytokines IL-1β, IL-16 and IL-23 in the tumor microenvironment in malignant melanoma." (PMID 36135194, 2022). "Solid tumours that have been shown to upregulate IL-1β include breast, colon, lung, and head and neck cancers and melanoma, and patients with these IL-1β-upregulated tumours generally show a poor prognosis." (PMID 35902905, 2022). "In mice, the NLRP3 inflammasome, IL-1β, and IL-18 support melanoma growth, migration, and metastasis." (PMID 36293159, 2022). "Melanoma cells often express variable levels of IL-1β and IL-6, which plays an important role of cell proliferation and melanoma progression." (PMID 36132145, 2022). "The most prominent components of the SASP in cytokine-treated melanoma cells were IL-1β, IL-6, and IL-8." (PMID 35563820, 2022). "In human melanoma cells, blocking the IL-1 pathway by IL-1α or IL-1β treatment increases autophagy-related components such as LC3-I and LC3-II, indicating an increase of autophagy." (PMID 36245983, 2022). "When melanoma cells were treated with IL-1β (100 pM) for 0–180 min, p65/RelA and p105 phosphorylation was observed at 5–15 min and 5–30 min after stimulation, respectively." (PMID 36445856, 2022). "In melanoma, a pro-inflammatory phenotype is induced in astrocytes exposed to melanoma exosomes that included the upregulation of IL-1α, IL-1β, CXCL1 and CCL2 among others." (PMID 36704194, 2022). "In the context of malignancy, IL-1β is a validated target in mouse models of cancer, including melanoma, where the cytokine contributes to immunosuppression, angiogenesis, metastasis, and regulation of myeloid-derived suppressor cells (MDSCs)." (PMID 33649199, 2021). "In this study, the immune-regulatory ability of melanoma CAFs was demonstrated by the ample production of several cytokines and chemokines, including IL-1α, IL-1β, IL-6, IL-8, and CXCL10." (PMID 34298873, 2021). "NLRP3 is particularly relevant to the processing of IL-1β in melanoma because NLRP3 is constitutively expressed in melanoma cell lines and NLRP3 polymorphisms are linked to increased risk to develop melanoma." (PMID 33649199, 2021). "We have previously shown that metastatic melanoma cells display constitutively active NLRP3 resulting in spontaneous IL-1β production and release." (PMID 34531850, 2021). "In melanoma models, IL-1B has been shown to increase the anti-tumour potential of T helper 1 (Th1) cells." (PMID 34290237, 2021). "Among the immune modulators involved in CAF activation, IL-1β seems to be a driver of melanoma invasion in vitro and in vivo." (PMID 34298873, 2021). "Levels of pro-inflammatory cytokines and chemokines including CXCL10, IFNα, IFNβ, IL-1b and TNFα increased with treatment in the majority of the melanoma tumoursphere lines tested." (PMID 34359633, 2021).
melanoma (continued). "In skin cancer, UV radiation is a powerful inducer of IL-1β, and melanoma-derived IL-1β is more likely to promote tumor growth, angiogenesis, invasion, and metastasis." (PMID 33686176, 2021). "The upregulation of IL-1β, IL-2, IL-6, and IL-12 mRNA expression was significant in PBMCs co-cultured with melanoma cells depigmented by both tyrosinase inhibitors, compared to pigmented cells." (PMID 34072104, 2021). "Among these cytokines, IL-1β was identified as a central melanoma cell-secreted factor involved in fibroblast activation and CAF differentiation." (PMID 34067929, 2021). "These in vitro findings demonstrate constitutive NLRP3 inflammasome activation in human melanoma cells and its role in the processing and secretion of IL-1β." (PMID 33649199, 2021). "In humans, IL-1β is overexpressed in biopsies from metastatic melanoma patients, suggesting a possible role in the melanoma-induced inflammation." (PMID 33649199, 2021). "These authors showed that a selective pharmacologic inhibitor of NLRP3, OLT1177, suppressed B16/F10 melanoma progression and inhibited IL-1β release in the 1205Lu human melanoma cell line." (PMID 34638239, 2021). "We recently reported that constitutively active NLRP3 in melanoma cells induces IL-1β and IL-6 in the host, resulting in the expansion of MDSCs." (PMID 34531850, 2021). "In melanoma, patients with advanced stage melanoma have elevated circulating levels of the proinflammatory cytokines IL‐1β and IL‐6, which correlate with poor prognosis." (PMID 34531850, 2021). "It has been reported that IL1B is highly expressed in solid cancers, including breast, colon, lung, head and neck cancers, and melanomas." (PMID 35008304, 2021). "In melanoma, tumor-derived IL-1β drives inflammation and the expansion of highly immunosuppressive myeloid-derived suppressor cells (MDSCs)." (PMID 34531850, 2021). "To determine the role of NLRP3 in IL-1β processing in melanoma, we specifically targeted NLRP3 in human melanoma cell lines." (PMID 33649199, 2021). "A high concentration of IL-1β has been detected in the plasma of patients with melanoma compared to healthy donors." (PMID 34604096, 2021). "Here, we link NLRP3 activity in melanoma cells to the IL-1β induced-IL‐6/STAT3 axis, thus providing an additional mechanism to target STAT3 signaling in melanoma." (PMID 34531850, 2021). "Our data indicate that Salmonella-treated melanoma influences reprogramming of macrophages into the M1-like phenotype, characterized by a significant increase in iNOS expression and IL-1β secretion." (PMID 34207850, 2021). "This work also reported an improved anti-tumor immune response when combining OLT1177 with anti-PD-1 antibody therapy in the B16/F10 melanoma model and inferred that this was due to inhibition of melanoma-dependent IL-1β secretion." (PMID 34638239, 2021). "CD73 promotes metastasis of breast cancer via the expression of EGFR and IL-8, while, CD73 blockade restrains melanoma metastasis through the formation of IL-1β and TNF-α." (PMID 32902664, 2021). "In this study, we observed that both recombinant and tumor-derived IL-1β specifically induce pSTAT3(Y705), creating a tumor-autoinflammatory loop, which amplifies IL-6 signaling in the human melanoma cell line 1205Lu." (PMID 34531850, 2021). "Taken together, our results show that melanoma-specific bcl-2 controls an IL-1β-driven axis of macrophage diversion that establishes tumor microenvironmental conditions favoring melanoma development." (PMID 32269145, 2020). "In contrast, elevated level of ASC inhibited NF-κB activity and affected processing of IL-1β in primary melanoma cells." (PMID 32340261, 2020). "IL-1β has been shown to be upregulated in many solid tumors, including melanoma, colon, lung, breast, or head and neck cancers and is associated with poorer prognosis." (PMID 32635472, 2020).